UGT1A7 (UDP glucuronosyltransferase family 1 member A7)
Diseases named in the same sentence as UGT1A7 in open-access papers:
UGT1A7 is named in the same sentence as 33 diseases in open-access papers, as found by Europe PMC text mining. Sharing a sentence is not in itself a finding about the gene and the disease. The quoted sentences say what the papers report.
colorectal cancer (7 papers, 2013 to 2024). A primary or metastatic malignant neoplasm that affects the colon or rectum. "There is a cancer risk associated with increased UGT1A7 *2 for the hepatocellular carcinoma and Asian groups and with increased UGT1A7 *3 for the hepatocellular carcinoma, colorectal carcinoma, Caucasian, and Asian groups." (PMID 29029519, 2017). "Our purpose was to examine the association between irinotecan toxicity and UGT1A1*28, UGT1A7*2, and UGT1A7*3 polymorphisms in Greek patients with colorectal cancer receiving low-dose irinotecan treatment." (PMID 24834123, 2014). "Polymorphism in UGT1A7 was an indicator of drug toxicity in colorectal cancer, but this polymorphic gene may be associated with drug toxicity in EOC." (PMID 30970615, 2019). "The analysis of a case-controlled study revealed increased risk of developing colorectal cancer (CRC) in individuals carrying UGT1A1*6 and UGT1A7*3 variants." (PMID 23468910, 2013). "The association of colorectal cancer (CRC) with UGT1A1*6 (G71R in exon-1), and UGT1A7*3 had been reported in Caucasoid, with an OR of 2.75; African Americans and American white; Chinese (Taiwan), with an OR of 2.75; and Chinese (mainland) with an OR of 4.9; and Chinese, with OR of 1.59." (PMID 23468910, 2013). "The UGT1A1*6, UGT1A7*3 and UGT1A9*22 genotypes were shown to be related to severe toxicity concordant with a Japanese study of FOLFIRI-treated colorectal cancer patients." (PMID 36239106, 2022). "UGT1A7*3 was found to be a risk factor for oropharyngeal cancer, hepatocellular carcinoma, and colorectal cancer (CRC), and a recent study showed that UGT1A7 plays a role in the glucuronidation of SN-38." (PMID 36239106, 2022). "Studies have also indicated that the UGT1A7 and/or UGT1A9 genotypes may be predictors of response and toxicity in colorectal cancer (CRC) patients treated with capecitabine and irinotecan." (PMID 39717480, 2024).
neutropenia (6 papers, 2010 to 2022). A decrease in the number of neutrophils found in the blood. "Among the patients who received targeted drugs, only UGT1A7*3 was found to be associated with a higher risk of G3–4 neutropenia incidence." (PMID 28637434, 2017). "Several studies have shown that UGT1A7*3 is associated with higher risk of suffering severe neutropenia." (PMID 28637434, 2017). "In total, 17 single nucleotide polymorphisms were identified, five of which revealed an association with grade 3/4 neutropenia, including UGT1A7*4; however, UGT1A1*28 and UGT1A1*6, which have been previously reported, were not significant." (PMID 25202427, 2014). "Furthermore, the H2 haplotype, which includes UGT1A9*22, and the H5 and H7 haplotypes, which include UGT1A7*2, UGT1A7*3 and UGT1A7*4, were associated with an increased risk of severe neutropenia." (PMID 25202427, 2014). "Additionally, H2 haplotypes, which include UGT1A9*22, and H5 and H7 haplotypes, which include UGT1A7*2, UGT1A7*3 and UGT1A7*4, were associated with a higher risk of severe neutropenia." (PMID 25202427, 2014). "In patients who experienced grade III–IV neutropenia, the UGT1A1*6, UGT1A7*3 and UGT1A9*22 polymorphisms showed significant associations only among those who received the weekly regimen (p = 0.015, p = 0.042, and p = 0.024, respectively)." (PMID 36239106, 2022). "Among patients who had any of the UGT1A1*6, UGT1A7*3 or UGT1A9*22 variants, 13 suffered grade III–IV neutropenia and 23 suffered grade III–IV diarrhea." (PMID 36239106, 2022). "The patients with UGT1A1*6 and UGT1A7*3 were prone to severe neutropenia, and the patients with UGT1A9*1b were prone to severe diarrhea." (PMID 29609559, 2018). "In total, five SNPs were identified to reveal a correlation with grade 3/4 neutropenia, including UGT1A7*4; however, the correlation with UGT1A1*28 and UGT1A1*6, which has been repeatedly reported, was not significant." (PMID 25202427, 2014). "Since variants of not only UGT1A1, but also other genes, including UGT1A7, UGT1A9, ABCB1 and ABCC2, have been reported to be involved in the occurrence of CPT-11-induced severe neutropenia, rare variants of these genes should be investigated in the future." (PMID 24932285, 2014). "This Korean irinotecan pharmacokinetics study might also explain our finding that UGT1A1*6, UGT1A7*3, and UGT1A9*22 were associated with severe diarrhea or neutropenia." (PMID 36239106, 2022). "Haplotype H7, which includes UGT1A7*2, UGT1A7*3 and UGT1A7*4, was found to correlate with the disease control rate (P=0.045); while haplotypes H2 and H5 were observed to correlate with a higher risk of severe neutropenia." (PMID 25202427, 2014). "Furthermore, inherited genetic variations in UGT1A1, UGT1A7 and UGT1A9 are associated with grade 3/4 neutropenia." (PMID 25202427, 2014). "Patients with the UGT1A9*1/*1 genotype were more likely to develop severe non-haematologic toxicity and diarrhoea, whereas UGT1A7*3/*3 genotype was also associated with the occurrence of neutropenia and diarrhoea simultaneously." (PMID 20628391, 2010). "UGT1A1*6, UGT1A7*3 and UGT1A9*1b should be monitored regularly to avoid the incidence of the severe neutropenia and diarrhea." (PMID 29609559, 2018). "In this study, UGT1A7*3 had a significant ability to predict severe neutropenia in univariate analysis, but the relationship did not appear to be significant in multivariate analysis." (PMID 28637434, 2017).
hepatocellular carcinoma (4 papers, 2007 to 2022). A malignant tumor that arises from hepatocytes. "With its low carcinogen metabolizing activity, UGT1A7 gene is a risk factor for hepatocellular carcinoma (HCC) development in, Chinese (OR = 3.06), French (OR = 3.4), Japanese (OR = 2.33), and Koreans (OR = 1.45)." (PMID 23468910, 2013). "We conducted a case-control study to evaluate the role of UDP-glucuronosyltransferase 1A7 (UGT1A7) polymorphisms in the onset of hepatocellular carcinoma (HCC)." (PMID 18021430, 2007).
pancreatic cancer (4 papers, 2015 to 2023). "In addition, a large number of valuable epidemiological studies have shown that UGT1A7 affects individuals’ susceptibility to various cancers, such as pancreatic cancer and gastrointestinal carcinomas." (PMID 33845800, 2021). "Second, the UGT1A7 polymorphism alleles contrast model and the categorized UGT 1A7 genotypes were compared, and the outcomes revealed that the ratio of UGT1A7*3 vs *2 increased, which may indicate an increased risk for cancer, especially for the pancreatic carcinoma and Caucasian groups." (PMID 29029519, 2017). "Among the remaining five candidate proteins, it has been reported that UGT1A7 may affect the progression of pancreatic cancer." (PMID 38054015, 2023).
breast carcinoma (3 papers, 2008 to 2021). "It is worth noting that the remaining genes, such as GNGT1 and UGT1A7, have not been documented to be associated with breast cancer." (PMID 35096840, 2021).
lung carcinoma (3 papers, 2012 to 2023). "It has been shown that polymorphisms in the UGT1A7 gene are associated with lung cancer, suggesting that these polymorphisms reduce enzymatic activity." (PMID 22768131, 2012).
Cirrhosis (2 papers, 2007 to 2010). A chronic disorder of the liver in which liver tissue becomes scarred and is partially replaced by regenerative nodules and fibrotic tissue resulting in loss of liver function. "In addition, UGT1A7 polymorphisms have been correlated with cirrhosis, and with increased risk of HCC in HBV- and HCV-infected patients." (PMID 20305825, 2010). "We have however no hypothesis to explain the difference in the relation between HCC and UGT1A7 according to cause of cirrhosis." (PMID 18021430, 2007). "Our study shows that UGT1A7 may play a role in hepatocellular carcinogenesis and that this role may differ according to the primary cause of the cirrhosis." (PMID 18021430, 2007). "Interestingly, the association between UGT1A7 and HCC risk seemed to differ according to characteristics of cirrhosis." (PMID 18021430, 2007). "The results for UGT1A7 appear to be related to the characteristics of cirrhosis." (PMID 18021430, 2007). "Inversely, we found a strong negative OR for this genotype (UGT1A7*3/*3) when we considered HCC and cirrhosis patients who were heavy drinkers and virus(-)." (PMID 18021430, 2007).
diabetes (2 papers, 2018 to 2023). "The results indicated that the pathological state of diabetes could significantly increase the mRNA and protein levels of Ugt1a1 and Ugt1a7 in rats." (PMID 29925761, 2018).
Hyperbilirubinemia (2 papers, 2020 to 2023). An increased amount of bilirubin in the blood. "In addition to ABCB1, we also analyzed variants in APOE and UGT1A7 pharmacogenes, associated with ritonavir induced dyslipidemia and hyperbilirubinemia, respectively." (PMID 33312066, 2020). "Additionally, patients treated with ritonavir could experience hyperbilirubinemia if they are carriers of UGT1A7 rs17868323 allele, whose prevalence in Serbian population is 62.9%." (PMID 33312066, 2020). "Haplotype UGT1A1, UGT1A3, UGT1A7 and MDR1 3435 have been associated with hyperbilirubinemia." (PMID 36691090, 2023). "We have shown that rather frequent PGx markers, ABCB1 rs1045642 and ABCB1 rs2032582 (AAF around 50%), could be relevant for reduced clearance of azithromycin, lopinavir and ritonavir drugs and UGT1A7 rs17868323 (AAF 66.2%) for hyperbilirubinemia in ritonavir treated COVID-19 patients in Serbia." (PMID 33312066, 2020).
maturity onset diabetes (2 papers, 2017 to 2023). "In both male and female type 2 diabetes-induced Sprague–Dawley rats treated with streptozotocin, consumption of a high-fat diet increased UGT1A1, UGT1A6, and UGT1A7 probe activities but decreased the UGT2B1 probe activity." (PMID 37034183, 2023).
metastatic colorectal cancer (2 papers, 2014). "UGT1A1*6 (211G>A), UGT1A1*28 (TA6>TA7), UGT1A1*60 (−3279T>G), UGT1A7 (387T>G), UGT1A7 (622T>C), and UGT1A9*1b (−118T9>T10, also named *22) were genotyped in 123 patients with metastatic colorectal cancer who had received irinotecan-based chemotherapy." (PMID 25175642, 2014).
bladder cancer (1 paper, 2013). "Downregulated gene products include putative tumor suppressor genes (SCUBE2), factors previously reported as lost in aggressive bladder cancer (FOXA1, GATA3, UPK3A), and metabolizing enzymes with polymorphisms affecting cancer risk (UGT1A10, UGT1A7)." (PMID 24134934, 2013).
chronic pancreatitis (1 paper, 2024). A chronic inflammatory process causing damage and fibrosis of the pancreatic parenchyma. "As for the UGT1A7 gene, rs11692021 polymorphism was related to higher risk of chronic pancreatitis (aOR = 1.76, 95% CI: 1.26–2.46)." (PMID 38408952, 2024).
colon cancer (1 paper, 2012). "More recently, another study demonstrated induction of UGT1A1 and UGT1A7 by irinotecan in colon cancer cells." (PMID 23110092, 2012).
gastric cancer (1 paper, 2022). A primary or metastatic malignant neoplasm involving the stomach. "In summary, our study shows a unique UGT1A genotype pattern in Korean gastric cancer patients and suggests that the presence of the UGT1A1*6, UGT1A7*3 and UGT1A9*22 polymorphisms in gastric cancer patients receiving irinotecan-containing treatment was significantly associated with severe toxicity." (PMID 36239106, 2022). "In this study, we analyzed the frequencies of important subtypes of UGT1A1, UGT1A7, and UGT1A9 in 382 Korean gastric cancer patients." (PMID 36239106, 2022).
glomerulonephritis (1 paper, 2014). A renal disorder characterized by damage in the glomeruli. "Since mycophenolic acid is a substrate for UGT1A7 and SLE and SVV patients have reduced UGT1A7 transcript expression relative to healthy controls, the glomerulonephritis patients would be predicted to have a lower metabolism of mycophenolic acid through UGT1A7 within the leukocytes." (PMID 24548980, 2014).
cancer (10 papers, 2007 to 2025). A tumor composed of atypical neoplastic, often pleomorphic cells that invade other tissues. "UGT1A7 can alter an individual’s susceptibility to cancer by decreasing the body’s detoxification capacity." (PMID 36741721, 2022). "First, the UGT 1A7 gene polymorphisms genotype in GIC patients were compared with a non-cancer control group, and second, the UGT1A7 polymorphism alleles contrast model and UGT 1A7 genotypes categorized according to enzymatic activity were examined." (PMID 29029519, 2017). "Further case-controlled studies of UGT1A7 gene polymorphisms should have a large sample size and should be robust and randomized to confirm the risks of cancer due to genotypes, particularly in patients with GIC." (PMID 29029519, 2017). "(2011) performed meta-analysis to demonstrate that there is a cancer risk associated with intermediate and low activity UGT1A7 genotypes." (PMID 28466663, 2017). "Secondly, subgroup analyses and meta-regressions were used to identify the differences between the different cancer types and ethnicities to determine which population has a higher risk of UGT1A7 gene polymorphisms." (PMID 29029519, 2017). "First, the main objective of the study was to determine the relationship between UGT1A7 gene polymorphisms and the risk of gastrointestinal cancer, whereas the previous pairwise studies included all cancer-related publications." (PMID 29029519, 2017). "It is suggested that the UGT1A7 *2 mutation is a cancer suppressor in the Caucasian population, while it promotes cancer in the Asian population, and the UGT1A7 *3 mutation is cancer-promoting." (PMID 29029519, 2017). "Previous literature has shown that the alteration of UGT1A7 activity is a key factor to determine the cancer risk." (PMID 28466663, 2017). "The findings of this comprehensive network meta-analysis provide some evidence that there are cancer risks associated with increased UGT1A7 *2 for the HCC and Asian groups and with increased UGT1A7 *3 for the HCC, CRC, Caucasian, and Asian groups." (PMID 29029519, 2017). "Other epidemiological studies of different cancer sites also suggest that low UGT1A7 detoxification activity is associated with a higher risk of cancer; one study was unable to confirm this result." (PMID 18021430, 2007). "In a study of 84 Japanese cancer patients, comprising 50 with colon cancer, 18 with stomach cancer, seven with ovarian cancer, seven with lung cancer, and two with other types of cancer, a genetic association between UGT1A7 and UGT1A9 polymorphisms and the UGT1A1-6 allele was reported." (PMID 40432911, 2025). "Finally, UGT1A7*4, which may be associated with an increased risk of cancer (1.16, 0.78 to 1.71), was accompanied by low heterogeneity (P = 0.289, I2 = 16.3%)." (PMID 29029519, 2017). "In a clinical setting, the genetic monitoring of UGT1A7 can be used as a predictor of cancer." (PMID 29029519, 2017). "Recently, UGT1A7 mutant-type (especially *3 and *4) gene polymorphisms have been identified as having a high risk of cancer, while others did not yield significant results." (PMID 29029519, 2017). "In addition, a significant increase was found only in the HCC group and Asian population group when UGT1A7*2 was compared in the cancer patient group and the control group." (PMID 29029519, 2017). "Secondly, the UGT1A7 polymorphism alleles contrast model and the categorized UGT 1A7 genotypes were compared, and the outcomes revealed that the increased ratio of UGT*3 vs *2 may indicate an increased risk of cancer, especially in the PC and Caucasian groups." (PMID 29029519, 2017). "Pairwise meta-analyses have been conducted to identify the cancer risk of different genotypes; however, only direct evidence was considered, and whether the UGT1A7 polymorphisms are a risk factor for cancer susceptibility was not investigated." (PMID 29029519, 2017).
cancer (continued). "The high expression of UGT1A8, UGT8, UGT1A7, UGT2A3, and UGT2B15 in these cancers and its relation to good patient prognosis is very interesting and deserves further investigation." (PMID 36741721, 2022). "Kaplan–Meier plots and logrank tests revealed that six UGT genes were significantly associated with increased overall survival (OS) rates [UGT1A1 (LUSC), UGT1A6 (ACC), UGT1A7 (ACC), UGT2A3 (KIRC), UGT2B15 (BLCA, SKCM)] or decreased OS rates [UGT2B15 (LGG), UGT8 (UVM)] in specific cancers." (PMID 34503303, 2021).
UGT1A7 also shares sentences with these, for which no sentence is quoted: cardiovascular diseases (1 paper); cholelithiasis (1); coronary heart disease (1); COVID-19 (1); diarrheal disease (1); dyslipidemia (1); endometrial cancer (1); gastrointestinal carcinomas (1); Gilbert syndrome (1); Hepatic fibrosis (1); Hepatitis (1); ischemic stroke (1); kidney disease (1); Lipedema (1); oropharyngeal cancer (1); respiratory infection (1).